ZNF513 (zinc finger protein 513)
Description:
Transcriptional regulator that plays a role in retinal development and maintenance.
Synonyms: FLJ32203; RP58; Zfp513; HMFT0656
Tractability: PROTAC: ubiquitination databases record sites on it.
Gene: Protein-coding gene on chromosome 2 (27,377,235 to 27,380,790, reverse strand). Ensembl gene ENSG00000163795.
Subcellular location: Nucleus
Gene Ontology:
Molecular function: DNA binding; protein binding; transcription cis-regulatory region binding; DNA-binding transcription factor activity
Biological process: retina development in camera-type eye; regulation of DNA-templated transcription
Cellular component: nucleus
Genetic constraint (gnomAD): Loss-of-function variants: 15 observed, 37.56 expected, observed/expected ratio (o/e) 0.4, 90% interval 0.27 to 0.62. The upper end of that interval is the gene's LOEUF score, 0.62, which puts it in group 2 of 6, group 1 being the genes least tolerant of losing a copy. Missense variants: 681 observed, 751.09 expected, observed/expected ratio (o/e) 0.91, 90% interval 0.85 to 0.97. Synonymous variants: 336 observed, 300.05 expected, observed/expected ratio (o/e) 1.12, 90% interval 1.02 to 1.23.
Homologues: Orthologues: chimpanzee ZNF513 (99% identical), macaque ZNF513 (99% identical), pig ZNF513 (98% identical), dog ZNF513 (98% identical), rabbit ZNF513 (97% identical), guinea pig ZNF513 (97% identical), rat Zfp513 (95% identical), mouse Zfp513 (95% identical), tropical clawed frog ZNF513 (52% identical), zebrafish znf513b (49% identical), zebrafish znf513a (46% identical), Drosophila melanogaster CG6654 (19% identical), and 2 more. Paralogues in human: ZNF324 (24% identical), ZNF324B (23% identical), ZBTB47 (21% identical), ZNF652 (17% identical), GTF3A (16% identical), ZUP1 (10% identical).
Diseases named in the same sentence as ZNF513 in open-access papers:
ZNF513 is named in the same sentence as 16 diseases in open-access papers, as found by Europe PMC text mining. Sharing a sentence is not in itself a finding about the gene and the disease. The quoted sentences say what the papers report.
autosomal recessive retinitis pigmentosa (2 papers, 2011 to 2023). Autosomal recessive retinitis pigmentosa (RP) is an autosomally recessive inherited retinal dystrophy leading to progressive loss of the photoreceptors and retinal pigment epithelium and resulting in blindness usually after several decades. "Mutations in at least one gene from each family have previously been associated with retinal disease: Klhl7 with autosomal dominant RP, Slc24A1 with autosomal-recessive congenital stationary night blindness, and Znf513 with autosomal-recessive retinitis pigmentosa (RP)." (PMID 22162623, 2011).
gingival tumor (1 paper, 2023). "The ChIP-qPCR and electrophoresis of NHGFs and patient gingival tumor fibroblasts confirmed that ZNF513 in these cells had clear binding at the enrichment peak of the SOS1 promoter region, and the binding sequence was confirmed to be the genomic sequence of SOS1." (PMID 37752101, 2023). "Furthermore, we observed that ZNF513 and KIF3C expression was significantly increased in patient gingival tumor tissue and primary gingival fibroblasts." (PMID 37752101, 2023).
tumor (1 paper, 2023). "The expression of KIF3C and ZNF513 in patient’s normal gingiva tissue was not significantly different from that in the control group, but the expression in tumor tissue was significantly increased." (PMID 37752101, 2023).
ZNF513 also shares sentences with these, for which no sentence is quoted: autosomal recessive congenital stationary night blindness (1 paper); cancer (1); connective tissue diseases (1); dyslipidemia (1); gingival fibromatosis (1); gingival hyperplasia (1); Hyperglycemia (1); Obesity (1); retinal degeneration (1); retinal disease (1); retinopathy (1); Stargardt disease (1); type 2 diabetes (1).